GADD45B (growth arrest and DNA damage inducible beta)
Description:
Involved in the regulation of growth and apoptosis. Mediates activation of stress-responsive MTK1/MEKK4 MAPKKK.
Synonyms: MYD118; GADD45BETA; DKFZP566B133
Tractability: No criterion of Open Targets' tractability assessment is met for any kind of drug.
Gene: Protein-coding gene on chromosome 19 (2,476,122 to 2,478,805, forward strand). Ensembl gene ENSG00000099860.
Subcellular location (Human Protein Atlas): Nucleoplasm; Cytosol; Nucleoli
Gene Ontology:
Molecular function: protein binding
Biological process: positive regulation of apoptotic process; positive regulation of JNK cascade; positive regulation of p38MAPK cascade; regulation of cell cycle
Cellular component: cytoplasm; nucleus
Genetic constraint (gnomAD): Loss-of-function variants: 9 observed, 14.56 expected, observed/expected ratio (o/e) 0.62, 90% interval 0.37 to 1.08. The upper end of that interval is the gene's LOEUF score, 1.08, which puts it in group 4 of 6, group 1 being the genes least tolerant of losing a copy. Missense variants: 150 observed, 200.85 expected, observed/expected ratio (o/e) 0.75, 90% interval 0.65 to 0.86. Synonymous variants: 95 observed, 91.45 expected, observed/expected ratio (o/e) 1.04, 90% interval 0.88 to 1.23.
Homologues: Orthologues: chimpanzee GADD45B (100% identical), macaque GADD45B (99% identical), dog GADD45B (98% identical), pig GADD45B (98% identical), guinea pig GADD45B (94% identical), mouse Gadd45b (93% identical), rat Gadd45b (92% identical), zebrafish gadd45bb (69% identical), zebrafish gadd45ba (68% identical), tropical clawed frog gadd45b (61% identical), Drosophila melanogaster Gadd45 (26% identical). Paralogues in human: GADD45A (56% identical), GADD45G (56% identical).
Diseases named in the same sentence as GADD45B in open-access papers:
GADD45B is named in the same sentence as 158 diseases in open-access papers, as found by Europe PMC text mining. Sharing a sentence is not in itself a finding about the gene and the disease. The quoted sentences say what the papers report.
hepatocellular carcinoma (15 papers, 2012 to 2025). A malignant tumor that arises from hepatocytes. "Although gadd45b seems infrequently mutated in cancer, reduced expression of Gadd45b gene due to promoter methylation was observed in hepatocellular carcinoma." (PMID 30279966, 2018). "Consistent with its broader immunomodulatory functions, GADD45β has been implicated in tumor-associated macrophages reprogramming and CD8 + T-cell recruitment in hepatocellular carcinoma." (PMID 41354733, 2025). "By contrast, Gadd45β plays a role in promoting apoptosis and inhibiting tumour function in hepatocellular carcinoma (HCC)." (PMID 39653679, 2024). "In hepatocellular carcinoma, GADD45B expression is decreased in tumor tissues and different hepatocellular carcinoma cell lines, while it remains unchanged in normal liver tissues and cell lines." (PMID 37608794, 2023). "Treatment with DNMT inhibitor 5‐azacytidine induces re‐expression of GADD45B and inhibits the proliferation of hepatoma cells." (PMID 37250145, 2023). "Gadd45β proteins are frequently particularly decreased expression in hepatocellular carcinoma (HCC)." (PMID 29225771, 2017). "In current study, we found that the overexpression of Gadd45β enhanced the chemotherapy induced apoptosis in hepatocellular carcinoma." (PMID 29225771, 2017). "The overexpression of GADD45B has been shown to inhibit cell growth in a variety of human tumor cell lines, including hepatocellular carcinoma cells, prostate cancer cells, breast cancer cells and others." (PMID 23110778, 2012). "In the present study, we demonstrated ZY0511 effectively inhibited hepatocellular carcinoma (HCC) cell proliferation by upregulating the expression of DNA damage‐inducible gene 45beta (GADD45B), a direct downstream target of lysine‐specific histone demethylase 1 (LSD1)." (PMID 37250145, 2023). "GADD45B acts as a critical regulator in the development of hepatocellular carcinoma." (PMID 37608794, 2023). "GADD45B has paradoxical effects: positively, it promotes proliferation, growth and cell survival, playing a dominant role in hepatocytes, while negatively, it inhibits proliferation and stimulates apoptosis, especially in hepatocellular carcinoma." (PMID 37405258, 2023). "An associated study indicated that GADD45B contributed to tumor progression rather than the initiation in hepatocellular carcinoma and ovarian cancer." (PMID 30029519, 2018). "Meanwhile, GADD45B might play critical roles in the tumorigenesis of human embryonic carcinoma, hepatocellular carcinoma, and pituitary gonadotrope tumors." (PMID 30029519, 2018). "In addition, the study indicated that the induction of Gadd45β promoted the therapeutic drug induced apoptosis in hepatocellular carcinoma." (PMID 29225771, 2017). "Recent studies have reported that GADD45B may play an important role in the carcinogenesis of human hepatocellular carcinoma and pituitary gonadotrope tumors, but its role in CRC remains unclear." (PMID 23110778, 2012). "Several studies have reported that GADD45B was decreased in human hepatocellular carcinoma (HCC)." (PMID 23110778, 2012). "Thus Gadd45β may be the potential target for enhancing the chemosensitivity of human hepatocellular carcinoma." (PMID 29225771, 2017). "Growth arrest DNA damage-inducible gene 45β (GADD45β), which influences cell growth, apoptosis and cellular response to DNA damage, is downregulated in hepatocellular carcinoma (HCC)." (PMID 27177086, 2016). "In fact, there are reports of elevated expression of FNDC5/irisin in human hepatocellular carcinoma (HCC) and our bioinformatic analysis also indicates that high expression of both GADD45β and FNDC5 negatively impacts the prognosis of cancer patients." (PMID 37746289, 2023). "Thus, Gadd45β may be a potential target for the therapy of hepatocellular carcinoma." (PMID 29225771, 2017).
hepatocellular carcinoma (continued). "We investigated the non-specific cytotoxic potential of DTP3 in the human hepatocellular carcinoma cell line, HepG2, which does not express GADD45β, using a multi-parametric toxicity assay, in vitro." (PMID 31080744, 2019). "However, the role of Gadd45β in the apoptosis of hepatocellular carcinoma is still not clear." (PMID 29225771, 2017).
multiple myeloma (14 papers, 2015 to 2023). "GADD45β is upregulated in MM cells by NF-kB, associates with poor outcome in patients, and promotes myeloma cell survival by suppressing proapoptotic MKK7/JNK signaling." (PMID 33396582, 2020). "Recent studies have shown that GADD45β plays an important role in multiple myeloma onset and maintenance." (PMID 34639041, 2021). "GADD45β is selectively and constitutively expressed in Multiple Myeloma cells, and this expression correlates with an unfavourable clinical outcome." (PMID 29572137, 2018). "Pharmacologically disrupting the GADD45B/MKK7 complex could restore MKK7/JNK activation in multiple myeloma." (PMID 33013461, 2020). "Therefore, we sought to selectively target the NF-κB oncogenic function in multiple myeloma cells by inhibiting the GADD45β/MKK7 survival module downstream in the NF-κB pathway." (PMID 29277662, 2018). "Consequently, GADD45β is highly expressed in most multiple myelomas, where it suppresses apoptosis ensuing from spontaneous JNK/MAPK-pathway activation by inhibiting the JNK kinase, MKK7." (PMID 29511335, 2018). "Since the GADD45β/MKK7 complex is critical for the NF-κB-driven survival, it is a promising therapeutic target in multiple myeloma." (PMID 34639041, 2021). "Recently, we identified the complex formed by GADD45β and the JNK kinase, MKK7, as an essential survival module dependent on constitutive NF-κB signalling and a novel therapeutic target in multiple myeloma." (PMID 29277662, 2018). "The interaction between NF-κB-regulated GADD45B and MKK7 has been identified as a potential therapeutic target in multiple myeloma." (PMID 29045468, 2017). "Blocking the interaction between the NF-κB-regulated anti-apoptotic protein GADD45b and the JNK kinase MKK7 has been suggested for treating multiple myeloma, leading to the development of the DTP3 peptide, which can kill cancerous cells without affecting normal cells." (PMID 37891174, 2023). "We demonstrated that GADD45β/MKK7-targeting agents are effective in killing multiple myeloma cells, ex vivo and in vivo, and, crucially, are not toxic to healthy tissues, as they preserve the physiological functions of NF-κB." (PMID 29511335, 2018). "We sought to overcome this problem in multiple myeloma by alternatively targeting the GADD45β/MKK7 signalling module in a non-redundant, cancer-restricted survival axis of the NF-κB pathway." (PMID 29511335, 2018). "Indeed, more recently, we have identified the complex formed by GADD45β and the JNK kinase, MKK7, as a functionally critical survival module downstream of NF-κB and novel therapeutic target in multiple myeloma." (PMID 28829404, 2017). "Due to this cancer-selective mode of action, GADD45β/MKK7 inhibitors demonstrated no adverse effects, alongside a cancer-selective pharmacodynamic response, in their first-in-human study in refractory multiple myeloma patients." (PMID 29511335, 2018). "GADD45β/MKK7 complex is a non-redundant, cancer cell-restricted survival module downstream of the NF-kB survival pathway, and it has a pathogenically critical role in multiple myeloma, an incurable malignancy of plasma cells." (PMID 33396582, 2020).
prostate carcinoma (11 papers, 2005 to 2025). A carcinoma that arises from epithelial cells of the prostate gland. "Previous studies have shown that GADD45B plays an important role in the proliferation and migration of ovarian cancer, prostate cancer, esophageal cancer, non-small cell lung cancer and other cancer cells." (PMID 40350499, 2025). "Studies have shown that GADD45B is considered a prognostic and predictive biomarker in colorectal cancer and that increased levels of GADD45B predict improved survival of prostate cancer patients." (PMID 33013461, 2020). "Studies have shown that matrine upregulates gadd45b expression via p38/JNK, ROS/gadd45b/p38 pathway, inhibits proliferation and migration of prostate cancer DU145, PC3 cells, and induces apoptosis, which is also associated with NF-κB pathway." (PMID 32477114, 2020). "Compared with the high levels of staining in colon cancer, breast cancer, prostate cancer, lymphoma, squamous cell carcinoma, and leiomyosarcoma, the under-expression of GADD45B was specific to liver cancer." (PMID 23110778, 2012). "GADD45B promoted chemosensitivity of prostate cancer through MAPK pathway." (PMID 34490266, 2021). "That study demonstrated its ability to activate specific genes—ZFP36, GADD45B, and SOCS3—in a prostate cancer cell line." (PMID 38543002, 2024). "GADD45b was recently identified as an EGR3-dependent gene in prostate cancer, and EGR3 was shown to bind to the GADD45B promoter in vivo and upregulate expression of GADD45B in vitro." (PMID 35941129, 2022). "Cumulatively, pro-apoptotic genes, such as XAF1 and GADD45B were down-regulated, whereas DRAM1 was up-regulated in the adipose tissue of prostate cancer patients." (PMID 23009291, 2012). "The induction of apoptosis mediated by GADD45A, GADD45B, PA25, and PIG11 could be another molecular mechanism by which Taxotere and/or Furtulon inhibit the growth of prostate cancer cells." (PMID 15656911, 2005).
colorectal cancer (10 papers, 2012 to 2024). A primary or metastatic malignant neoplasm that affects the colon or rectum. "Analysis results according to the stage II CRC cohort and the liver metastatic CRC cohort revealed that GADD45B was gradually upregulated in normal mucosa including primary colorectal cancer (PCC)." (PMID 30029519, 2018). "This study aimed to explore the potential relationship between GADD45B expression and tumor progression and evaluate the clinical value of GADD45B in stage II colorectal cancer (CRC)." (PMID 30029519, 2018). "GADD45B overexpression has been recently correlated with shorter overall survival in colorectal carcinoma." (PMID 30537927, 2018). "In light of previous scientific inquiries, it’s compelling to mention that many of the genes within this list of 10, specifically CAV1, DAPK1, GPX3, IGFBP6, TIMP1, GADD45B and ENO2 have been found associated intimately with colorectal cancer, as documented by several research studies." (PMID 38501104, 2024). "Evidence has indicated that the up-regulated expression of GADD45B is correlated with an advanced stage and decreased OS in patients with colorectal cancer, and it may be an independent prognostic factor for patients with papillary thyroid carcinoma." (PMID 35699863, 2022). "Likewise, high GADD45B protein expression was an independent marker of poorer prognosis in stage II colorectal cancer and a potential marker to indicate post-operative chemotherapy." (PMID 32425887, 2020). "However, the promoting role of GADD45B in tumorigenesis or rapid disease progression was also reported in colorectal carcinoma, gastric, and ovarian cancer." (PMID 33330109, 2020). "The expression of ACSL4 was significantly upregulated while the expression of GADD45B was significantly downregulated in the HCC tumor tissues compared to matched normal tissues or histologically normal liver tissues from colorectal cancer patients who had liver metastases." (PMID 28900541, 2017). "The aim of this study is to detect the role of GADD45B in colorectal carcinoma (CRC); the area not studied in depth to date." (PMID 23110778, 2012).
Stroke (10 papers, 2015 to 2026). Sudden impairment of blood flow to a part of the brain due to occlusion or rupture of an artery to the brain. "Deficient DNA repair is closely associated with poor neurological outcomes after stroke, whereas upregulation of specific DNA repair enzymes such as APE1, OGG1, XRCC1, and Gadd45b can enhance long-term functional recovery after stroke." (PMID 39583099, 2024). "In middle cerebral artery occlusion/reperfusion rats, Alk5, known as TGF‐β type I receptor, was found to regulate neural plasticity and functional recovery via Gadd45b, a molecule with key role in anti‐apoptosis and DNA repair in stroke." (PMID 34693660, 2021). "In our previous studies, growth arrest and DNA damage protein 45b (Gadd45b) mediated axonal plasticity after stroke." (PMID 31043581, 2019). "Specifically, PPARα KO led to increased expression levels of Gadd45b, Nppa, Hdc, Lcn2, Il6, Sox4, Marcksl1, Saa3, Ucn2, Met, Dusp10, Elovl7, Ngf, C3, Il11, Hmox1, Alox5, Tnfsf9, Angptl4, Plin2, H19, Csf2rb, Atf3, and Col7a1 following stroke." (PMID 40362325, 2025). "Brain ischemia induces the expression of Gadd45b, which stimulates recovery after stroke and may play a protective role in cerebral ischemia." (PMID 26698301, 2015). "Our results showed that Gadd45b stimulated recovery after stroke, and may play a protective role in cerebral ischemia." (PMID 26698301, 2015). "Multivariate logistic regression analysis revealed that among the molecular variables, DUSP1 (OR = 2.39, 95% CI: 0.87–6.57; p = 0.092) and GADD45B (OR = 2.53, 95% CI: 0.63–10.22; p = 0.192) showed a trend toward stroke association, though neither reached statistical significance." (PMID 40636523, 2025). "This article provided an overview of the preclinical and clinical effects of Gadd45b, as well as its hypothesized mechanisms of action, focusing on major psychosis, depression, autism, stroke, seizure, dementia, Parkinson’s disease, and autoimmune diseases of the nervous system." (PMID 36311022, 2022). "Therefore, Gadd45b may be a new target for stroke treatment." (PMID 36311022, 2022). "Demethylation by TET1, TET3, and Gadd45b controls the expression of galanin, Ng2, bdnf, fgf-1, RAG, and Bdnf IV in the neurorepair mechanism in stroke." (PMID 36142283, 2022).
breast cancer (9 papers, 2012 to 2025). A primary or metastatic malignant neoplasm involving the breast. "The underlying mechanisms described so far are manifold and include activation of ERK via GADD45β in breast cancer or stimulation of the pathway at the receptor levels via HER1/EGFR." (PMID 40782795, 2025). "The overall survival data showed that the prognosis of breast cancer patients was poorer when two genes (FOS and FOSB) were highly expressed or when four genes (JUN, GADD45B, NR4A1, and BTG2) showed low expression levels." (PMID 34457116, 2021). "Eight of these genes (except WNT2, GADD45B, FZD2, WNT7B, POLK, and PIK3R3) have been extensively studied in breast cancer." (PMID 32818022, 2020). "“All of the mouse and most human mammary tumors also displayed decreased expression of genes known to inhibit cell proliferation, including NFKBIA (IKBalpha), GADD45B, and CDKN1A (p21); transcription-related genes such as CEBP, JUN, JUNB, and ELF1;....”." (PMID 23216862, 2012). "Notably, during the developmental trajectory of cells, breast cancer stem cells (BCSCs) tend to express genes such as IER3 and GADD45B at the early stage, while genes like NNMT and LDHB are preferentially expressed in the BCSCs-2 developmental state." (PMID 40092692, 2025).
colon cancer (9 papers, 2012 to 2025). "In specific colon cancer cells, GADD45β over-expression was linked to protection from platin induced death, matching our observations." (PMID 22983756, 2013). "According to reports in the literature, higher expressions of GADD45B are associated with a higher risk of recurrence based on a cluster analysis of patients with stage II/III colon cancer treated with surgery alone or surgery plus adjuvant fluorouracil plus leucovorin." (PMID 23110778, 2012). "Patients with stage II colon cancer and high levels of GADD45B expression have shown poor overall survival (OS) and progression-free survival (PFS) rates." (PMID 37608794, 2023). "Moreover, a recent integrative analysis of multiple colon cancer gene-expression-based subtype classifiers reported that one of the three highest scoring genes included in several classifiers was GADD45B." (PMID 30537927, 2018). "However, no direct correlation between survival and GADD45B expression in colon cancer has been described earlier." (PMID 27849044, 2016).